METTL14 (methyltransferase 14, N6-adenosine-methyltransferase non-catalytic subunit)
Diseases named in the same sentence as METTL14 in open-access papers (continued):
Sharing a sentence is not in itself a finding about the gene and the disease.
hepatocellular carcinoma (continued). "In hepatocellular carcinoma (HCC), downregulation of METTL14 results in lower m6A levels, and enhances the metastatic capacity of HCC cells." (PMID 28533023, 2017). "Current evidence suggests that WTAP regulates ferroptosis in hepatoma cells, which recruits METTL3 and METTL14, promoting the m6A methyltransferase to bind with RNA." (PMID 39744575, 2025). "METTL14-mediated m6A modification stabilizes USP48 mRNA, linking epigenetic regulation to TME metabolic remodeling and hepatocellular carcinoma suppression." (PMID 40986143, 2025). "In hepatocellular carcinoma (HCC), METTL14 plays a key role in immune escape." (PMID 41164187, 2025). "In hepatocellular carcinoma (HCC), M1 macrophage–derived exosomes deliver miR-628-5p to suppress METTL14, reducing circFUT8 methylation and nuclear export." (PMID 41164187, 2025). "In hepatocellular carcinoma (HCC), METTL14 binds DGCR8 and facilitates m6A-dependent processing of pri-miR-126." (PMID 41301491, 2025). "For instance, exosomes derived from M1 macrophages inhibit the expression of human methyltransferase-like 14 (METTL14) in hepatocellular carcinoma (HCC) cells by transferring miR-628-5p, while METTL14 promotes m6A modification of circFUT8, facilitating its cytoplasmic export." (PMID 40034598, 2025). "For human liver carcinoma HepG2 cells with different bile acids, the results showed that the mRNA m6A writers METTL3 and METTL14 can be down‐regulated by most bile acids, except lithocholic acid." (PMID 38713722, 2024). "Meanwhile, hypoxia increases SLC7A11 by inhibiting methyltransferase-like 14 (METTL14) to suppress ferroptosis by decreasing ROS, which promotes hepatocellular carcinoma (HCC) progression." (PMID 37458878, 2023). "In hepatocellular carcinoma (HCC), particularly in metastatic HCC, m6A modification is reduced, METTL14 is identified as the core molecule regulating abnormal m6A modification of HCC." (PMID 34904301, 2022). "Meanwhile, METTL14 induced m6A methylation of hepatocyte nuclear factor 3γ (HNF3γ) mRNA, a hepatocyte nuclear factor, leading to reduced HNF3γ expression in hepatocellular carcinoma (HCC)." (PMID 35859892, 2022). "In hepatocellular carcinoma (HCC), METTL-14 can also interact with DGCR8." (PMID 36553003, 2022). "METTL-14 inhibits the expression of miRNA 126, and downregulation of METTL-14 is an adverse prognosis factor in hepatocellular carcinoma." (PMID 36553003, 2022). "In hepatocellular carcinoma and glioblastoma, several reports have revealed the consistent oncogenic roles of METTL3 and METTL14 in these two cancer types." (PMID 36360287, 2022). "METTL14 can directly recruit DCGR8 on the m6A-coded pri-miRNA to stimulate the expression of the oncosuppressor, miR-126a, in hepatocellular carcinoma (HCC)." (PMID 33898522, 2021). "METTL14 interacts with DGCR8 to modulate pri-miR-126 and suppresses the metastatic potential of hepatocellular carcinoma (HCC)." (PMID 31142332, 2019). "In a recent study, METTL14 and METTL3 have been demonstrated to be downregulation in hepatocellular carcinoma." (PMID 31429529, 2019). "In addition, it has also been shown that, in hepatocellular carcinoma (HCC), METTL14 can directly recruit DCGR8 on the m6A modified pri-miRNA encoding for oncosuppressor miR-126a." (PMID 31316981, 2019). "In 2017, one study found that m6A modification decreased in hepatocellular carcinoma (HCC), especially in metastatic HCC, and METTL14 was responsible for the aberrant m6A modification in this kind of cancer." (PMID 30149601, 2018). "Meanwhile, METTL14 is down-regulated in cancers such as triple-negative breast cancer (TNBC), esophageal cancer (EC), osteosarcoma (OS), hepatocellular carcinoma, and nephroblastoma, and its low expression has been associated with poor prognosis in cancer patients." (PMID 39289775, 2024).
hepatocellular carcinoma (continued). "Interestingly, research has found that HBV infection results in an increase in METTL14 expression levels in chronic HBV patients, HBV-positive hepatocellular carcinoma (HCC) patients, and primary human hepatocytes infected with HBV." (PMID 39513116, 2024). "In hepatocellular carcinoma (HCC), METTL14 was identified to be involved in the malignant progression of HCC by regulating m6A downstream targets, including cysteine sulfinic acid decarboxylase (CSAD), glutamic- oxaloacetic transaminase 2 (GOT2), and suppressor of cytokine signaling 2 (SOCS2)." (PMID 35731272, 2023). "In hepatocellular carcinoma (HCC), the upregulation of METTL3 and downregulation of METTL14 may contribute to HCC progression and metastasis, causing a poor prognosis of patients." (PMID 36051357, 2022). "In addition, METTL14 was identified to interact with DGCR8 and regulate the pri‐miR‐126 mature process in an m6A‐dependent manner in hepatocellular carcinoma." (PMID 32808488, 2020). "In human hepatoma cells (HCC), decreased m6A and METTL14 was detected and overexpression of METTL14 can interact with DGCR8 to regulate the maturation of pri-miRNA126 in an m6A-dependent manner, reducing the metastasis of hepatoma cells." (PMID 32898471, 2020). "Moreover, one study showed that high m6A modification promoted hepatocellular carcinoma progression which was ascribed to high METTL3 expression, while another study believed that was ascribed to low METTL14 expression." (PMID 31230592, 2019). "Targeting regulators like METTL3, METTL14, the IGF2BP family, ALKBH5, or FTO can enhance the efficacy of PD-1 blockade therapy in renal clear cell carcinoma, colorectal cancer, melanoma, NSCLC, breast cancer, hepatocellular carcinoma, and intrahepatic cholangiocarcinoma." (PMID 39372415, 2024). "Current research has illuminated the pivotal role of RNA m6A methyltransferase complex components, particularly METTL3 and METTL14, in the pathogenesis and progression of cancers, including acute myeloid leukemia (AML) and hepatocellular carcinoma (HCC)." (PMID 39329012, 2024). "In hepatocellular carcinoma (HCC), silencing METTL3 and METTL14 has been shown to reduce the level of circRNA-SORE, which acts as a miRNA sponge by recruiting miR-103a-2-5p and miR-660-3p to competitively activate the Wnt/β-catenin pathway, thereby inducing sorafenib resistance." (PMID 34315512, 2021). "METTL14 was shown to exert its oncogenic role by regulating MYB and MYC through m6A modification in acute myeloid leukemia (AML), whereas it also suppressed tumorigenesis and metastasis of bladder cancer or hepatocellular carcinoma (HCC)." (PMID 34149792, 2021).
breast cancer (98 papers, 2018 to 2025). A primary or metastatic malignant neoplasm involving the breast. "In gastric cancer and breast cancer, lower grade of expression of METTL14 is associated with poorer prognosis, while overexpression of METTL14 in certain types of tumors is related to tumor proliferation and metastasis." (PMID 41323393, 2025). "The up-regulation of METTL14 plays a better diagnostic role in the peripheral blood screening of breast cancer." (PMID 39289775, 2024). "METTL14 has also been implicated as an oncogene in breast cancer, another endocrine-driven cancer, as well as in pancreatic cancer and AML." (PMID 36733939, 2022). "Low METTL14 expression was associated with worse recurrence-free survival in HER2-positive breast cancer." (PMID 35562334, 2022). "Another study showed that the loss of METTL14 caused reduced expression of downstream TGF-β genes in breast cancer cells." (PMID 35966596, 2022). "We examined the association between METTL14 expression, cancer progression, and patient prognosis in a total of 398 breast cancer tissue specimens." (PMID 33134390, 2020). "It appears that downregulated METTL14 expression in breast cancer is associated with tumor grade and molecular classification." (PMID 33134390, 2020). "Therefore, we speculate that METTL14 reduction causes the upregulation of FGFR4 expression in HER2-positive breast cancer." (PMID 35562334, 2022). "Furthermore, the same authors report that METTL14 levels are reduced in breast cancer and they are associated with low survival rates, suggesting that METTL14 could potentially regulate m6A modification of miRNAs also in this type of tumour." (PMID 33564819, 2021). "LINC00942 has been linked to prognosis and immune responses in hepatocellular and bladder cancers and promotes METTL14-mediated m6A methylation in breast cancer." (PMID 40034693, 2025). "PAK5 kinase acts on its targets mainly through phosphorylation and we overexpressed PAK5 in breast cancer cells and identified METTL14 with a phosphorylation site at serine 399 using phosphorylation mass spectrometry." (PMID 40258843, 2025). "Our results indicate that PAK5 phosphorylates METTL14 at serine 399 and the phosphorylation of METTL14 S399 site in breast cancer tissues is more active than that in normal tissues." (PMID 40258843, 2025). "Secondly, when it comes to breast cancer metastasis, METTL14, functioning as an m6A methyltransferase, has been convincingly demonstrated to promote the growth and migration of breast cancer cells." (PMID 39972939, 2025). "Nevertheless, the downregulation of METTL14 is considered an important factor in the tumorigenesis and metastasis of breast cancer cells, possibly functioning relies on affecting the factors’ expression related to the Wnt signaling pathway." (PMID 41323393, 2025). "METTL14-regulated DEGs included both oncogenic and tumour suppressor genes and demonstrate a role of METTL14 in regulating metabolism in breast cancer." (PMID 41310336, 2025). "The RIP analysis showed the binding of METTL14 to MALAT1 in breast cancer cells and the MeRIP-PCR assays indicated that METTL14 knockdown significantly reduced m6A modification of MALAT1 in BT474 cells." (PMID 40258843, 2025). "In breast cancer, METTL14 is frequently downregulated, correlating with ER-/PR-/triple-negative subtypes, poor prognosis, and advanced progression." (PMID 41164187, 2025). "In contrast, it has been elucidated that METTL14 regulates m6A modification on hsa-miR-146a-5p to suppress its expression and increase breast cancer cells migration and invasion capacity." (PMID 38075202, 2024). "Consistently, the protein expression of METTL14 was diminished in multiple MSL TNBC cell lines compared with that in luminal breast cancer cells." (PMID 39563370, 2024). "For instance, METTL14 has been identified as an inhibitor of breast cancer cell proliferation, colony formation, and migration, while also diminishing the growth and self-renewal of glioblastoma stem cells." (PMID 39219199, 2024).
breast cancer (continued). "It was found that in breast cancer cells, the METTL14–apoptosis axis plays an important role in the early diagnosis, treatment, and prognostic assessment of breast cancer." (PMID 38785921, 2024). "METTL14 has been reported to exert contrasting effects, promoting the growth and metastasis of pancreatic cancers and breast cancers." (PMID 39103890, 2024). "Our findings are consistent with previous studies that METTL14 is highly expressed in breast cancer and higher expressed in TNBC." (PMID 38263865, 2024). "Further exploration of the mechanisms by which NANOG cooperates with METTL14 to maintain breast cancer stemness is necessary to answer this question." (PMID 39563370, 2024). "Another investigation showed that an lncRNA promotes the progression of ER+ and HER2+ breast cancer by promoting METTL14-mediated m6A modification." (PMID 39563370, 2024). "In breast cancer (BC), METTL14 can be stabilized by AURKA by inhibiting proteasomal‐dependent degradation." (PMID 36260366, 2023). "Adversely, METTL14 plays a pro-tumorigenic function in breast cancer by determining the m6A levels of EMT and angiogenesis-related transcripts such as TWIST." (PMID 37437245, 2023). "The expression of METTL14 is also up-regulated in breast cancer tissues, thus promoting breast cancer cell migration and invasion by regulating the expression of hsa-miR-146a-5p." (PMID 37805597, 2023). "Another study showed a similar result: high expression of circMETTL3 induced by METTL14-mediated m6A modification leads to breast cancer cell migration and invasion." (PMID 37437245, 2023). "Up to now, the regulatory effects of LncRNAs on METTL14 is mainly observed in breast cancer and acute myeloid leukemia (AML)." (PMID 37365581, 2023). "It is noteworthy that the METTL14-apoptosis axis plays role in early diagnosis, treatment and prognosis evaluation for breast cancer." (PMID 35090469, 2022). "LNC942, a lncRNA predominantly located in the cytoplasm, was reported to bind directly to a methyltransferase, METTL4, and promote METTL14‐mediated RNA m6A methylation in breast cancer." (PMID 35073459, 2022). "Western blot assays also confirmed that METTL14 expression was decreased in trastuzumab-resistant breast cancer cells." (PMID 35562334, 2022). "Other subunits of METTL3 complex, namely WTAP, RBM15, KIAA1429 (also known as Virilizer homolog or VIRMA), and METTL14, displayed moderate-to-strong staining intensities in both normal and breast cancer tissues." (PMID 36289222, 2022). "In breast cancer, aurora kinase A (AURKA) positively regulates METTL14 protein expression by inhibiting its ubiquitylation‐mediated degradation to elevate DROSHA m6A content to improve DROSHA mRNA stability in breast cancer stem‐like cells." (PMID 34904301, 2022). "In breast cancer, the stability and expression of METTL14 are positively regulated by LNC942, which elevates the m6A content in downstream targets CXCR4 and CYP1B1, stabilizes protein expression and translation, and further promotes tumorigenesis." (PMID 34904301, 2022). "It was showed that METTL14 increased the expression of has-miR-146a-5p and promoted the invasion and migration of breast cancer." (PMID 35721510, 2022). "Knockdown of METTL14 significantly increased the expression level of FGFR4 in HER2-positive breast cancer cells." (PMID 35562334, 2022). "At the same time, the oncogenic role of METTL14 has been also uncovered in pancreatic cancer, breast cancer and so on." (PMID 36288387, 2022). "METTL14 has been reported to mediate the m6A modification in the modulation of colorectal cancer, breast cancer, and HCC." (PMID 36474147, 2022). "It has been unveiled that LINC00942 serves as an oncogene by promoting METTL14-mediated m6A methylation in breast cancer." (PMID 34238292, 2021).
breast cancer (continued). "In HCC and CRC, METTL14 inhibits the occurrence of tumors by promoting the synthesis of tumor-suppressor miRNAs, whereas in breast cancer, METTL14 promotes the occurrence and development of tumors by enhancing the synthesis of tumor-promoting miRNAs." (PMID 34108450, 2021). "It has been verified that hsa-miR-146a-5p is a differentially expressed miRNA, modulated by METTL14-induced m6A modification, and thus affects the migration and invasion of breast cancer cells." (PMID 35004679, 2021). "For example, in breast cancer cells, METTL14 promotes cancer cell invasion and migration, but in colorectal cancer, METTL14 inhibits proliferation and metastasis." (PMID 33237585, 2021). "In breast cancer, increased expression of METTL14 enhances m6A RNA modifications and has-miR-146a-5p expression, ultimately enhancing breast cancer cell invasion and migration." (PMID 34660577, 2021). "Recent studies have shown that LINC00942 potentiated breast cancer cell proliferation and progression by affecting METTL14-mediated m6A methylation." (PMID 34987577, 2021). "LNC942 was found to interact with the m6A regulator METTL14 to facilitate the molecular function of breast cancer cells." (PMID 34743750, 2021). "Previously, METTL14, an m6A methyltransferase, was proven to regulate breast cancer cell migration through m6A modification." (PMID 34508078, 2021). "Findings from three investigations into METTL14 expression and function in breast cancer are controversial, with one study showing that METTL14 acts as a tumor suppressor, while the other two show that METTL14 promotes cancer growth." (PMID 33134390, 2020). "To further elucidate the downstream molecular mechanism involved in METTL14 and ZC3H13 by regulating m6A in breast cancer, we selected a set of 76 common positively co-expressed genes of METTL14 and ZC3H13." (PMID 33363011, 2020). "This study performed an IHC analysis of METTL14 expression in breast cancer tissue samples obtained from 398 Chinese Han women, to clarify the expression of METTL14 in breast cancer and its clinicopathological and prognostic significance." (PMID 33134390, 2020). "Around half of the breast cancer tissue specimens (52.8%, 210/398) expressed high METTL14 expression, compared with 75.0% (18/24) of normal breast tissue specimens; the between-group difference was significant (P = 0.034)." (PMID 33134390, 2020). "In conclusion, our study revealed that METTL14 and ZC3H13, as two tumor suppressor genes, were down-regulated in breast cancer, and the low expression of METTL14 and ZC3H13 was negatively correlated with the OS and RFS." (PMID 33363011, 2020). "In one study, significantly decreased METTL14 expression was observed in patients with breast cancer compared with healthy controls, and overexpression of METTL14 inhibited breast cancer cell viability, colony formation, and migration." (PMID 33134390, 2020). "METTL14 promotes the migration and invasion of breast cancer cells by directly regulating hsa-miR-146a-5p and m6A modification." (PMID 33292526, 2020). "Association between mRNA expression of METTL14, ZC3H13 and clinicopathological characteristics in breast cancer patients (TCGA)." (PMID 33363011, 2020). "We also found in this study that METTL14 expression was significantly decreased in younger-aged women (≤35 years), who have been shown to have more aggressive breast cancer and a worse prognosis." (PMID 33134390, 2020). "Our analysis showed that having higher-grade disease, the TNBC subtype or the HER2-enriched subtype is independently correlated with low METTL14 expression in breast cancer." (PMID 33134390, 2020). "After excluding cases with incomplete clinical data of TCGA breast cancer patients from UCSC Xena, 637 cases were included to analyzed the association of METTL14 and ZC3H13 expression with clinical and pathological features through chi-squared test." (PMID 33363011, 2020).